RN7SKP4 (RN7SK pseudogene 4)
Gene: Miscellaneous RNA gene on chromosome 13 (45,123,093 to 45,123,414, forward strand). Ensembl gene ENSG00000271818.
Homologues: Orthologues: chimpanzee 7SK (92% identical). Paralogues in human: 7SK (74% identical), RN7SKP203 (72% identical), RN7SKP79 (71% identical), RN7SKP174 (71% identical), RN7SKP180 (71% identical), RN7SKP217 (71% identical), RN7SKP62 (71% identical), RN7SKP48 (70% identical), RN7SKP133 (70% identical), RN7SKP118 (70% identical), RN7SKP189 (70% identical), RN7SKP3 (70% identical), and 284 more.